ALG2 (ALG2 alpha-1,3/1,6-mannosyltransferase)
Description:
Mannosyltransferase that operates in the biosynthetic pathway of dolichol-linked oligosaccharides, the glycan precursors employed in protein asparagine (N)-glycosylation. The assembly of dolichol-linked oligosaccharides begins on the cytosolic side of the endoplasmic reticulum membrane and finishes in its lumen. The sequential addition of sugars to dolichol pyrophosphate produces dolichol-linked oligosaccharides containing fourteen sugars, including two GlcNAcs, nine mannoses and three glucoses. Once assembled, the oligosaccharide is transferred from the lipid to nascent proteins by oligosaccharyltransferases. Catalyzes, on the cytoplasmic face of the endoplasmic reticulum, the addition of the second and third mannose residues to the dolichol-linked oligosaccharide chain, to produce Man3GlcNAc(2)-PP-dolichol core oligosaccharide. Man3GlcNAc(2)-PP-dolichol is a substrate for ALG11, the following enzyme in the biosynthetic pathway. While both alpha 1,3 and alpha 1,6 linkages are possible, the sequential addition of alpha 1,3 followed by alpha 1,6 is probably the preferred route.
Synonyms: CDGIi; FLJ14511; hALPG2; NET38; CDG1I; CMS14; CMSTA3
Tractability: PROTAC: ubiquitination databases record sites on it; its protein half-life has been measured.
Gene: Protein-coding gene on chromosome 9 (99,216,425 to 99,221,942, reverse strand). Ensembl gene ENSG00000119523.
Subcellular location: Endoplasmic reticulum membrane
Subcellular location (Human Protein Atlas): Golgi apparatus
Pathways (Reactome):
Disease: Defective ALG2 causes CDG-1i
Metabolism of proteins: Biosynthesis of the N-glycan precursor (dolichol lipid-linked oligosaccharide, LLO) and transfer to a nascent protein
Gene Ontology:
Molecular function: alpha-1,3-mannosyltransferase activity; GDP-Man:Man(1)GlcNAc(2)-PP-Dol alpha-1,3-mannosyltransferase activity; GDP-Man:Man(2)GlcNAc(2)-PP-Dol alpha-1,6-mannosyltransferase activity; protein binding; glycosyltransferase activity
Biological process: dolichol-linked oligosaccharide biosynthetic process; glycoprotein biosynthetic process; protein N-linked glycosylation
Cellular component: cytoplasmic side of endoplasmic reticulum membrane; endoplasmic reticulum membrane; membrane; endomembrane system
Genetic constraint (gnomAD): Loss-of-function variants: 32 observed, 30.53 expected, observed/expected ratio (o/e) 1.05, 90% interval 0.79 to 1.41. The upper end of that interval is the gene's LOEUF score, 1.41, which puts it in group 5 of 6, group 1 being the genes least tolerant of losing a copy. Missense variants: 574 observed, 515.67 expected, observed/expected ratio (o/e) 1.11, 90% interval 1.04 to 1.19. Synonymous variants: 253 observed, 217.86 expected, observed/expected ratio (o/e) 1.16, 90% interval 1.05 to 1.29.
Gene-disease validity (ClinGen):
ClinGen rates the evidence that ALG2 causes each of these diseases.
ALG2-congenital disorder of glycosylation (autosomal recessive): Strong. A form of congenital disorders of N-linked glycosylation characterized by iris coloboma, cataract, infantile spasms, developmental delay and abnormal coagulation factors.
Homologues: Orthologues: chimpanzee ALG2 (99% identical), macaque ALG2 (97% identical), pig ALG2 (91% identical), dog ALG2 (90% identical), rabbit ALG2 (90% identical), guinea pig ALG2 (89% identical), rat Alg2 (81% identical), mouse Alg2 (81% identical), tropical clawed frog alg2 (66% identical), zebrafish alg2 (65% identical), Drosophila melanogaster Alg2 (50% identical), Caenorhabditis elegans algn-2 (45% identical). Paralogues in human: ALG11 (24% identical), PIGA (15% identical), GLT1D1 (14% identical).
Diseases named in the same sentence as ALG2 in open-access papers:
ALG2 is named in the same sentence as 39 diseases in open-access papers, as found by Europe PMC text mining. Sharing a sentence is not in itself a finding about the gene and the disease. The quoted sentences say what the papers report.
congenital myasthenic syndrome (6 papers, 2019 to 2025). Congenital myasthenic syndrome (CMS) is a group of genetic disorders of impaired neuromuscular transmission at the motor endplate characterized by fatigable muscle weakness. "Given that ALG2 is one of the fourteen genes implicated in Congenital Myasthenic Syndrome, a deeper understanding of tissue-specific pathophysiology may help link clinical manifestations to ocular involvement in CDG patients." (PMID 41190328, 2025). "Mutations in the ALG2 gene were also associated with Congenital Myasthenic Syndrome." (PMID 41190328, 2025). "Additionally, ALG2 variants can cause congenital myasthenic syndrome type 14 (ALG2-CMS, OMIM#616228), which presents within the first decade of life, progresses slowly." (PMID 41437099, 2025).
breast carcinoma (4 papers, 2017 to 2024). "Our results reveal that ALG-2 is markedly upregulated in breast cancer tissues and is associated with various clinicopathological parameters indicative of tumor malignancy." (PMID 27926525, 2017). "To investigate the association between ALG-2 expression and breast cancer, we performed immunohistochemical staining to analyze the expression of ALG-2 in samples from patients who underwent surgical resection." (PMID 27926525, 2017). "Because ALG-2 overexpression was correlated with characteristics associated with poor prognosis of breast cancer patients, we next analyzed the effects of ALG-2 knockdown in vivo using a mouse xenograft model." (PMID 27926525, 2017). "We next analyzed associations between ALG-2 upregulation and clinical features of breast cancer." (PMID 27926525, 2017). "ALG2, a protein capable of binding calcium ions, displays high expression levels in cancerous tissues such as hepatocellular carcinomas, breast carcinomas, lung carcinomas, and gliomas." (PMID 39238386, 2024). "Previous findings demonstrating that ALG-2 is dysregulated in several cancer types led us to investigate its role in breast cancer." (PMID 27926525, 2017). "Our data also show that ALG-2 has an important function in breast cancer growth and metastasis by regulating cytoskeletal components and stimulating cell proliferation and migration." (PMID 27926525, 2017). "Taken together, these data indicate that ALG-2 depletion inhibits breast cancer growth and metastasis in vivo." (PMID 27926525, 2017). "ALG-2 was undetectable or marginally detectable in the majority of adjacent tissues, but strong expression of ALG-2 was observed predominantly in the cytoplasm of breast cancer cells." (PMID 27926525, 2017). "To gain insight into the functions of ALG-2 in the pathogenesis of breast cancer, we analyzed its effects on cell proliferation and survival in vitro." (PMID 27926525, 2017). "Our data also show that reduced ALG-2 expression interferes with the proliferative and metastatic potential of human breast cancer cells in a rodent xenograft model and in vitro." (PMID 27926525, 2017). "Here, we demonstrate that the expression of ALG-2 is significantly upregulated in breast cancer tissues and is correlated with clinicopathological characteristics indicative of tumor malignancy." (PMID 27926525, 2017). "We found that 89.5% of breast cancer tissues, but only 26.1% of adjacent tissues, exhibited elevated expression of ALG-2 (++ and +++)." (PMID 27926525, 2017). "Together, these findings suggest that ALG-2 plays a role in the regulation of microtubule rearrangement in migrating breast cancer cells." (PMID 27926525, 2017). "Our results demonstrate that ALG-2 overexpression in breast cancer cells disrupts the localization of γ-tubulin and pericentrin and results in the formation of centrosome protein aggregates." (PMID 27926525, 2017). "Our study demonstrates that ALG-2 plays a role in the regulation of cytoskeletal rearrangement that drives cell polarization and migration in breast cancer cells." (PMID 27926525, 2017). "Because abnormal cell motility is a requirement for cancer metastasis, we performed wound healing and transwell assays to assess the role of ALG-2 in the motility of breast cancer cells." (PMID 27926525, 2017). "In this study, we demonstrate that ALG-2 expression is markedly elevated in breast cancer tissues and is correlated with clinicopathological characteristics." (PMID 27926525, 2017). "ALG-2 also promotes breast cancer cell proliferation, survival, and motility in vitro." (PMID 27926525, 2017). "We also investigated whether ALG-2 plays a role in breast cancer metastasis by injecting 4T1-luc cells, mouse breast cancer cells expressing luciferase, into the tail veins of BALB/c mice." (PMID 27926525, 2017). "In addition, ALG-2 drives the polarization and migration of breast cancer cells by facilitating the rearrangement of microtubules and microfilaments." (PMID 27926525, 2017).
breast carcinoma (continued). "Our data further show that ALG-2 stimulates breast cancer growth and metastasis in mice." (PMID 27926525, 2017). "Taken together, these data indicate that ALG-2 is critical for breast cancer cell motility." (PMID 27926525, 2017). "At present, it is unknown whether ALG-2 is involved in the pathogenesis of breast cancer." (PMID 27926525, 2017). "Expression levels of ALG1, ALG2, ALG3, ALG8, ALG9, ALG12 and ALG13 were differentially upregulated in radioresistant breast cancer tissues compared with those in radiosensitive tissues, particularly ALG3 with the highest level (4.53-fold change)." (PMID 33931075, 2021). "Absence of ALG-2 expression (−) was only observed in 3.6% of breast cancer samples." (PMID 27926525, 2017).
epilepsy (4 papers, 2017 to 2025). A brain disorder characterized by episodes of abnormally increased neuronal discharge resulting in transient episodes of sensory or motor neurological dysfunction, or psychic dysfunction. "Variants in the ALG2 gene (NM_003087) are associated with ALG2-CDG, also known as CDG Ii (OMIM#607906), which is characterized by neurological symptoms such as convulsive syndrome, epilepsy, axial hypotonia, mental and motor regression." (PMID 41437099, 2025).
congenital disorder of glycosylation (3 papers, 2021 to 2025). Congenital disorder of glycosylation (CDG) is a fast growing group of inborn errors of metabolism characterized by defective activity of enzymes that participate in glycosylation (modification of proteins and other macromolecules by adding and processing of oligosaccharide side chains). "Pathogenic variants in DPAGT1 and ALG2 can also cause congenital disorders of glycosylation (CDG type Ij), which are associated with developmental delay and intellectual disability." (PMID 40442802, 2025).
developmental delay (3 papers, 2017 to 2025). "Pathogenic variants of DPAGT1 and ALG2 were reported in congenital disorder of glycosylation Ij (CDG Ij) with infantile spasms, developmental delay, microcephaly, and finger malformations." (PMID 36835142, 2023).
lung carcinoma (3 papers, 2017 to 2024). "Whereas ALG-2 expression levels were reported to be unrelated to patient survival in breast, colon, and lung cancers, ALG-2 has been shown to be a potential prognostic biomarker for predicting clinical efficacy in certain types of cancers." (PMID 33503978, 2021). "High expression of ALG-2 has been reported in liver and lung cancers, suggesting that the protein plays a role in survival pathways." (PMID 27926525, 2017). "ALG-2 has been found to be upregulated in lung cancer and liver cancer tissues." (PMID 27926525, 2017).
gastric cancer (2 papers, 2010 to 2021). A primary or metastatic malignant neoplasm involving the stomach. "Subsequently, overexpression of ALG-2 in ovarian and advanced gastric cancer cells was reported to show synergic inhibition of cell viability in combination with treatment of anticancer drugs, cisplatin and 5-FU." (PMID 33503978, 2021). "Recent clinical investigations suggest that ALG-2 is a potential prognostic marker of certain lung and gastric cancers." (PMID 20691033, 2010).
ovarian carcinoma (2 papers, 2017 to 2022). A malignant neoplasm originating from the surface ovarian epithelium. "In addition, ALG-2 has been implicated in ovarian cancer progression, and it may be an independent predictor of progression-free survival." (PMID 27926525, 2017). "To gain insight into changes in mannosyltransferases (ALGs), which have been found (ALG1, ALG2, ALG3, ALG9, ALG11 and ALG12) in ovarian cancer, we queried publicly available transcriptomic data, including Gene Expression Omnibus (GEO, GSE18520) and The Cancer Genome Atlas (TCGA) datasets." (PMID 36231102, 2022).
Parkinson disease (2 papers, 2022 to 2024). A progressive degenerative disorder of the central nervous system characterized by loss of dopamine producing neurons in the substantia nigra and the presence of Lewy bodies in the substantia nigra and locus coeruleus. "TRPML1 interacts with apoptosis-linked gene 2 (ALG2) and JNK-interacting protein 4 (JIP4), thereby promoting lysosomal clustering around the microtubule organizing center in cell models of Parkinson’s disease." (PMID 39650798, 2024).
retinitis pigmentosa (2 papers, 2021 to 2025). Retinitis pigmentosa (RP) is an inherited retinal dystrophy leading to progressive loss of the photoreceptors and retinal pigment epithelium and resulting in blindness usually after several decades. "The discovery of misregulated retina-specific proteins and the eventual loss of rod photoreceptors in the model hint at retinitis pigmentosa as a fish-specific or potentially thus far unnoticed human phenotype for ALG2-CDG." (PMID 34106226, 2021). "We suggest that this model focuses on how defects in the Alg2 enzyme, which is crucial for N-glycosylation, affect Alg2 protein in the retinal cells, under conditions like retinitis pigmentosa, as observed in patients." (PMID 41190328, 2025).
ductal carcinoma in situ (1 paper, 2017). "ALG-2 expression was low in ductal carcinoma in situ, whereas a significant increase in ALG-2 expression was observed in invasive breast carcinoma." (PMID 27926525, 2017).
polycystic ovary syndrome (1 paper, 2022). A disorder that manifests as multiple cysts on the ovaries. "The relationship between α-1,3/1,6 mannosyltransferase (ALG2) and ovulation is being investigated in patients with polycystic ovary syndrome." (PMID 36611913, 2022).
cancer (6 papers, 2016 to 2021). A tumor composed of atypical neoplastic, often pleomorphic cells that invade other tissues. "Apoptosis-linked gene 2 (ALG-2) is a calcium-binding protein crucial for diverse physiological processes and has recently been implicated in cancer development." (PMID 27926525, 2017). "ALG-2 has been reported to interact with cancer- or apoptosis-associated Ser/Thr-kinases such as Raf-1 and DAPK1 (death-associated protein kinase 1) in a Ca2+-dependent manner but with ASK1 Ca2+-independently." (PMID 27571067, 2016). "Since its identification more than 20 years ago, ALG-2 has attracted a lot of attention regarding its exact roles in T cells, cancer cells, and various other secretory cells." (PMID 31919392, 2020). "ALG-2 is associated with cancer development, and clinical investigation of cancer cells and tissues have revealed the usefulness of monitoring the expression of ALG-2 (often quoted PDCD6) as a biomarker for prognosis." (PMID 27571067, 2016). "The results of these studies suggest that ALG-2 may have an important role in killing of cancer cells in response to cytotoxic agents." (PMID 33503978, 2021). "These ESCRT-I subunits may also be predictive biomarkers of chemotherapy efficacy in cancer patients by combination with ALG-2." (PMID 33503978, 2021). "The calcium binding protein ALG-2 is upregulated in several types of cancerous tissues and cancer cell death may be a consequence of ALG-2 downregulation." (PMID 30240438, 2018). "Therefore, CDIP1 would be a potential target for ALG-2 in cancer patients undergoing chemotherapy." (PMID 33503978, 2021). "Thus, ALG-2 could function as a proapoptotic protein by interacting with CDIP1 in response to intracellular Ca2+ mobilization in cancer cells expressing CDIP1." (PMID 33503978, 2021). "Recent studies suggest that changes in ALG-2 expression may contribute to cancer development." (PMID 27926525, 2017). "Whereas no direct mechanistic role for ALG-2 in cancer cell viability has been identified, recent discoveries have linked ALG-2 to membrane vesicle traffic and cargo packaging via its interaction with Sec31A." (PMID 30240438, 2018).
tumour (5 papers, 2013 to 2020). "The mammalian GLD-1 homologue QKI has been reported to co-localize and interact with ALG2, and recently QKI was shown to directly interact with and stabilize miR-20a, revealing a role for QKI in tumour suppression." (PMID 24258276, 2013). "ALG1 and ALG3 classified the tumours as COX-2 positive or negative using experimentally determined cut-off thresholds (mean or median value of the score) while ALG2 based on arbitrarily determined cut-off value of 10%." (PMID 25269624, 2014).
infection (3 papers, 2013 to 2024). The state of being infected such as from the introduction of a foreign agent such as serum, vaccine, antigenic substance or organism. "In turn, infection caused a sharp increase in the expression levels of alg-2 at 2 hphs and its levels remained high until 8 hphs (χ2 = 117.538, 3 d.f., p < 0.001), at which point the expression of alg-2 also increased in control animals." (PMID 39137892, 2024). "Conversion from incident to older infection status among these 7 algorithms occurred first for Alg3 (gp41 band ≤0.5), tightly followed by Alg3.1 (gp41≤1) and Alg5 (p24≤0.5), Alg6 (p17≤0.5), Alg14, Alg2 (gp120≤1) and finally Alg4 (p31 = 0)." (PMID 23990968, 2013). "Mtb caused significantly more inflammasome activation and pyroptosis both in ALG-2 and ALIX KD macrophages after 24 h of infection, compared with control cells." (PMID 32385301, 2020).
ALG2 also shares sentences with these, for which no sentence is quoted: congenital disorder of glycosylation type II (2 papers); myopathies (2); Ataxia (1); Cerebral atrophy (1); Cognitive impairment (1); congenital muscular dystrophies (1); epileptic encephalopathies (1); fucosidosis (1); Gaucher disease (1); genetic disorder (1); glioma (1); glycogen storage disease types II (1); hepatocellular carcinoma (1); Intellectual disability (1); invasive breast carcinoma (1); lymph node metastasis (1); lysosomal storage disorders (1); metastasis (1); methylmalonic aciduria type cblA (1); neuropathy (1); Noonan syndrome (1); Rafiq syndrome (1); thyroid cancer (1); viral infections (1).